MTOR (mechanistic target of rapamycin kinase)
Diseases named in the same sentence as MTOR in open-access papers (continued):
Sharing a sentence is not in itself a finding about the gene and the disease.
gastric cancer (continued). "In gastric cancer, NOX2 has been found to be highly expressed in tumor tissues, and the NOX2-ROS axis can mediate the activation of tumorigenesis-associated pathways, including the Akt-mTOR, Stat3, and NF-κB signaling pathways." (PMID 41441930, 2025). "The PI3K/AKT/mTOR axis is hyperactivated in advanced gastric cancer." (PMID 41215803, 2025). "The unannotated compound in Cluster 1, GSK‐1059615, is identified as a PI3K and MTOR dual inhibitor which, in gastric cancer cells, potently inhibited cell growth, survival, proliferation, and the cell cycle potentially decoupling MYC from its control over cell proliferation." (PMID 41025936, 2025). "Berberine induced autophagy in gastric cancer via the MAPK-dependent mTOR/p70S6K signaling pathway." (PMID 41007776, 2025). "Co-activation of Notch and mTOR pathways drives gastric cancer proliferation." (PMID 40755759, 2025). "It is also really interesting that the phosphoinositide 3-kinase (PI3K)/AKT/mTOR and mitogen-activated protein kinase (MAPK) pathways can also be activated by Helicobacter pylori, one of the major risk factors for gastric cancer that is responsible for merely 80% of cases." (PMID 40227324, 2025). "Moreover, naringin (2 μM) induced autophagy and significantly reduced gastric cancer growth by downregulating the PI3K/Akt/mTOR cascade and activating MAPKs, suggesting its potential as a natural therapeutic enhancer in adenocarcinoma." (PMID 40559911, 2025). "Moreover, by inhibiting PI3K/AKT/mTOR pathway, TA can significantly increase the autophagy level of HepG2/2.2.15 cells and gastric cancer HGC-27 cells, leading to autophagy death of tumor cells." (PMID 41150819, 2025). "Moreover, NUP37 facilitates the PI3K/AKT/mTOR pathway to accelerate tumorigenesis in gastric cancer." (PMID 38955795, 2024). "However, the combination of the two significantly enhanced the antitumor effect in gastric cancer AGS cells by suppressing the PI3K/Akt/mTOR pathway." (PMID 38794206, 2024). "Since the PI3K/AKT/mTOR/HIF-1α axis drives tumour-promoting inflammation in H. pylori- and EBV-associated gastric cancer, agents that target this pathway may also inhibit the development of premalignant gastric lesions from completing malignancy." (PMID 39816318, 2024). "mTOR pathway is the downstream mediator of ALDH1A3 in gastric cancer." (PMID 39394200, 2024). "Cell proliferation and metabolism are regulated by PI3K/AKT/mTOR pathways in gastric cancer." (PMID 39524138, 2024). "The activation of p‐PI3K, p‐AKT, and p‐mTOR was observed in gastric cancer with increasing grade." (PMID 39524138, 2024). "Thus, the mTOR/eIF4E pathway exposed the vulnerability of gastric cancer by accelerating the production of aberrant peptides and boosting immune activation through W>F substitutant events." (PMID 38994917, 2024). "KIRREL may mediate the proliferation and angiogenesis of gastric cancer cells through the PI3K/AKT/mTOR signalling pathway." (PMID 37909722, 2024). "In contrast, FOXO6 promotes gastric cancer cell proliferation through cMyc induction, and its loss inhibits colorectal cancer cell proliferation, invasion and glycolysis, with decreased PI3K/AKT/mTOR pathway activation." (PMID 39499086, 2024). "Importantly, we reported for the first time that CLDN18.2-directed ADCs induced cytoprotective autophagy in gastric cancer treatment, with involvement of the Akt/mTOR signaling pathway." (PMID 39227365, 2024). "The lncRNA H19 and its mature product, miR-675, increase AKT/mTOR signaling in gastric cancer through the lncRNA-H19/miR-675/RUNX1 axis, whereas in gallbladder cancer, the same lncRNA can act as an endogenous competing RNA (ecRNA) by decoying miR-294-5p to increase AKT expression." (PMID 39614261, 2024).
gastric cancer (continued). "The PI3K/AKT/mTOR pathway has become a “hot spot” of molecular biomarker-based/targeted therapy because research in several types of cancer, such as breast, liver, colorectal, prostate, and gastric cancers, shows the presence of irregularities in this pathway." (PMID 39713250, 2024). "Additionally, alterations in ARID1A interact with the PI3K/Akt/mTor pathway in nasopharyngeal carcinoma and gastric cancer cell lines." (PMID 38600891, 2024). "Moreover, cynaroside, derived from Alpinia katsumadai, suppresses cyclin D1 expression and regulates the MET/AKT/mTOR signaling pathway, inhibiting both proliferation and migration of gastric cancer cells." (PMID 39906672, 2024). "Furthermore, molecular docking and western blot experiments confirmed that gypenoside induced the apoptosis of gastric cancer cells through the PI3K/AKT/mTOR signaling pathway." (PMID 38482051, 2024). "Furthermore, research on gastric cancer cells using AGS and MKN28 cells showed the ability of pectolinaringen to inhibit the viability of human gastric cancer cells via the AKT/PI3K/mTOR pathway." (PMID 39713250, 2024). "Given this, we speculate that the Sema6D expression level may affect the activation level of ERK and PI3K/AKT/mTOR signaling pathways in gastric cancer patients, thus affecting the proliferation and migration ability of gastric cancer cells." (PMID 40777970, 2024). "Moreover, mesenchymal-type gastric cancer cell lines were found to be sensitive to agents targeting the PI3K/AKT/mTOR pathway, suggesting that GC can be targeted with AKT inhibitors." (PMID 39614261, 2024). "Moreover, through a comprehensive network pharmacology analysis of the potential sites of action of gypenosides in gastric cancer, we found that the PI3K/AKT/mTOR pathway plays a crucial role in the apoptosis of gastric cancer cells." (PMID 38482051, 2024). "KIF23 plays a key role in cell proliferation, metabolism, differentiation, metastasis and survival through the activation of PI3K/AKT/mTOR and Wnt/β/Linker protein signaling pathway, and has been demonstrated in cancers such as gastric cancer and diffuse large B-cell lymphoma." (PMID 38818376, 2024). "Notch and mTOR signaling pathways promote human gastric cancer cell proliferation." (PMID 38675376, 2024). "In addition, we verified the PI3KA/AKT/mTOR pathway by western blot in three different gastric cancer cell lines." (PMID 36898991, 2023). "In summary, PTPN14 promotes the PI3KA/AKT/mTOR pathway in gastric cancer." (PMID 36898991, 2023). "Above of all, our results suggested that YWHAH could promote the proliferation of gastric cancer cells by activating the PI3K/AKT/mTOR signaling pathway." (PMID 37415737, 2023). "Regarding the anti-tumor effects of tipifarnib, we have reported that tipifarnib also exerts anti-tumor effects through the suppression of Rheb farnesylation, leading to the inhibition of the mTOR pathway other than via suppression of HIF-1α in gastric cancer cells." (PMID 37511305, 2023). "Thus, NFkB activated PI3KA expression and prompted PI3KA/AKT/mTOR pathway, accelerating gastric cancer cell proliferation, migration, and invasion." (PMID 36898991, 2023). "Therefore, the results suggested that suppressing the N-glycosylation of EpCAM by VH-F12 induces autophagic cell death via PI3K/Akt/mTOR pathway in gastric cancer cells." (PMID 37834237, 2023). "This indicates the addition of mTOR inhibitors may present a new therapeutic approach to tackling trastuzumab resistance in HER2-positive gastric cancer." (PMID 37877107, 2023). "This was true since LMP2A could downregulate AQP3 by inhibiting mTOR signaling pathway to promote autophagy of gastric cancer cells." (PMID 38089478, 2023). "Rhein and RAD001 inhibit gastric cancer through PI3K/Akt/mTOR." (PMID 36829987, 2023). "Furthermore, myricetin inhibits the PI3K/Akt/mTOR pathway, commencing autophagy and apoptosis, which lowers the survival rate of gastric cancer cells." (PMID 37298616, 2023).
gastric cancer (continued). "Furthermore, NFkB upregulates the expression of PI3KA and activates PI3KA/AKT/mTOR pathway to promote gastric cancer cell proliferation, migration, and invasion." (PMID 36898991, 2023). "Interestingly, mTOR is a pharmacologic target of autophagy, and the exploration of chemotherapy drugs of gastric cancer can continue from autophagy by mTOR." (PMID 36937439, 2023). "The results of KEGG pathway analysis suggested that PI3K-Akt signaling pathway, MAPK signaling pathway, Human papillomavirus infection, mTOR signaling pathway were significantly enriched which have been already known as the key signals in regulating several cancers including gastric cancer." (PMID 36366842, 2023). "Similarly, induction of gastric cancer cell autophagy via downregulation of the PI3K/Akt/mTOR signaling pathway was reported with thymoquinone, as a bioactive lactone, isolated from seed oil of Nigella sativa." (PMID 36428613, 2022). "The transcriptomic results showed that n-butylidenephthalide, the active compound in Angelicae Sinensis Radix, induced REDD1 (regulated in development and DNA damage responses 1) and consequently inhibited its downstream factor mammalian target of rapamycin (mTOR) in gastric cancer." (PMID 36523499, 2022). "Silencing of AURKB may decrease the invasive and migratory capacities of gastric cancer cells by disrupting the VEGFA/Akt/mTOR and Wnt/-catenin/Myc pathways." (PMID 35354488, 2022). "The PI3K/AKT/mTOR signaling is one of the most frequently dysregulated pathways in gastric cancer." (PMID 35089117, 2022). "The purpose of this study was to explore whether TOB1 induces autophagy through the AKT/mTOR signaling pathway in gastric cancer." (PMID 35186488, 2022). "Furthermore, Zhang and colleagues reported that circNrip1 promoted gastric cancer progression as a microRNA-149-5p sponge through the Akt1/mTOR pathway." (PMID 35655923, 2022). "Gαi 1 silencing or knockout inhibited Akt-mTOR activation and gastric cancer cell growth." (PMID 35280670, 2022). "Additionally, it is demonstrated that S100A10 promotes the malignant growth of cancer cells by activating the AKT/mTOR signaling pathway in osteosarcoma and the Src/ANXA2/AKT/mTOR signaling pathway in gastric cancer." (PMID 36612197, 2022). "Recent studies have shown that MALAT1 enhances the expression of serine-rich arginine splicing factor 1 (SRSF1) and activates the mammalian rapamycin target (mTOR) signaling pathway to promote the formation of gastric cancer (GC) and hepatocellular carcinoma (HCC)." (PMID 35208500, 2022). "Soysterol can also induce apoptosis and protective autophagy in gastric cancer cells by inhibiting the Akt/mTOR pathway and may be a potential anticancer drug for the treatment of gastric cancer." (PMID 36313365, 2022). "In addition, western blot data revealed that high TOB1 protein levels were associated with the formation of autophagosomes by suppressing the phosphorylation activation of AKT and mTOR in gastric cancer cells." (PMID 35186488, 2022). "The AKT/mTOR pathway is frequently activated in various tumor types (including gastric cancer)." (PMID 35186488, 2022). "The positive expression of p-mTOR was more frequent in advanced gastric cancers." (PMID 36046250, 2022). "Celastrol may inhibit the proliferation of cisplatin-resistant gastric cancer cells, induce their apoptosis, and reduce the expression of drug-resistant genes by inhibiting the expression of proteins related to the mTOR signal pathway." (PMID 36506508, 2022). "EIF3B may function as an oncogenic protein that activates the PI3K/AKT/mTOR pathway in gastric cancer." (PMID 36051357, 2022). "Moreover, previous studies showed PI3K/Akt/mTOR signaling pathway as an important signaling pathway in lipid metabolism in gastric cancer." (PMID 36713557, 2022).
gastric cancer (continued). "In accordance with the present results, previous studies have demonstrated that EIF3B downregulation suppresses cell proliferation, migration and invasion, and induces cell apoptosis by blocking the β-catenin pathway in endometrial cancer or the PI3K/AKT/mTOR pathway in gastric cancer." (PMID 35040374, 2022). "Recently, inhibition of CypA was shown to significantly suppress the proliferation of gastric cancer cells by downregulating the CD147-mediated phosphatidylinositol-3-kinase (PI3K)/AKT/mammalian target of rapamycin (mTOR), c-Jun N-terminal kinase (JNK), and ERK1/2 pathways." (PMID 36012604, 2022). "CXCL5 could recruit monocytes to form more M2-polarized macrophages and further promote the development of chemoresistance through the activation of PI3K/AKT/mTOR pathway in gastric cancer." (PMID 36151545, 2022). "Combining these results, the authors believed that stigmasterol induced apoptosis and protective autophagy in gastric cancer cells while inhibiting the Akt/mTOR signaling pathway, and they thought stigmasterol was likely to become a potential anticancer agent in future gastric cancer treatment." (PMID 36578938, 2022). "The PI3K/Akt/mTOR signaling pathway is commonly accepted as a vital pathway involved in various human cancers, and mediating epithelial-mesenchymal transformation and chemoresistance is considered to be the major factor promoting gastric cancer progression." (PMID 35368661, 2022). "Besides, several inhibitors of the PI3K/Akt/mTOR signaling pathway were successfully developed in drug research and their efficacy was tested in gastric cancer with significant improvement." (PMID 35256584, 2022). "In a Balb/c nu/nu tumor transplantation model, CD4+ T cells are reported to upregulate PD-L1 expression in gastric cancer-derived MSCs (GC-MSCs) via the p-STAT3 signaling pathway, and to activate the PD-1/mTOR signaling pathway, thereby promoting gastric cancer growth." (PMID 36439438, 2022). "The PI3K/AKT/mTOR signaling pathway regulates apoptosis in gastric cancer." (PMID 36038533, 2022). "Moreover, we identified that KP-SeNPs induce apoptosis and autophagy of AGS gastric cancer cells by suppressing the PI3K/Akt/mTOR pathway." (PMID 36209164, 2022). "In this study, a GSEA analysis and western blotting demonstrated that LMOD1 could alter the migration ability of gastric cancer cells by regulating FAK-Akt / mTOR pathway." (PMID 35488236, 2022). "At present, previous studies of our group have revealed that the overexpression of TOB1 can induce autophagy in gastric cancer cells, and its mechanism may be related to the down-regulation of Akt/mTOR signaling pathway." (PMID 35465266, 2022). "Among the oncogenic pathways involved in the emergence and development of gastric cancer are the PI3K/AKT/mTOR, Wnt/β-catenin, NF-κB, MAPK, Notch, and inflammatory signaling pathways, which could be regulated by noncoding RNAs." (PMID 35089117, 2022). "Indeed, previous studies have shown that gastric cancer patients with simultaneous expression of PI3K/p-AKT/p-mTOR had worse outcome." (PMID 34457026, 2021). "Thus, LPA enhances geminin stability via the LPAR3/MMPs/EGFR/PI3K/mTOR signaling axis in gastric cancer." (PMID 34658851, 2021). "CSE1L silencing could induce apoptosis and repress the proliferation and invasion of gastric cancer cells by regulating the PI3K/Akt/mTOR and MEK/ERK signaling pathways." (PMID 33842377, 2021). "Therefore, mTOR pathway was considered as a therapeutic target for cancer, including gastric cancer." (PMID 34234860, 2021). "Thus, LPA promotes S-phase cell-cycle progression in gastric cancer cells via the LPAR3/MMPs/EGFR/PI3K/mTOR signaling axis." (PMID 34658851, 2021). "However, many previous findings have reported of entirely different actions of salidroside on Akt/mTOR signaling in human colorectal cancer cells and human gastric cancer AGS cells." (PMID 34457117, 2021).
gastric cancer (continued). "Here, our findings indicated that SS could induce apoptosis and autophagy by blocking Akt/mTOR pathway, and autophagy played a protective role against SS-induced apoptosis in gastric cancer cells." (PMID 33708631, 2021). "Moreover, Akt/mTOR mediates the therapeutic effects of many natural herbs’ extracts on gastric cancer." (PMID 33627124, 2021). "LncRNAs were also involved in modulating mTOR pathway in gastric cancer." (PMID 34234860, 2021). "Mechanistically, knockdown of LIT3527 induced apoptosis and autophagy of gastric cancer cells may through inhibiting the mammalian target of rapamycin (mTOR) pathway." (PMID 34234860, 2021). "Likewise, antisense noncoding RNA in the INK4 locus (ANRIL) enhances proliferation and tumorigenesis by epigenetically silencing miR-99a/miR-449a, and consequently upregulating mTOR and cyclin-dependent kinase 6 downstream pathways in gastric cancer." (PMID 33668685, 2021). "Given our observation, LPA stabilized geminin via the LPAR3/MMPs/EGFR/PI3K/mTOR signaling axis in gastric cancer cells, we examined whether this pathway modulated cell-cycle progression." (PMID 34658851, 2021). "In gastric cancer, high expression of TTK is associated with poor prognosis of the patients, and depletion of TTK suppresses the proliferation and induces the apoptosis of gastric cancer cells via modulating Akt-mTOR signaling." (PMID 34516342, 2021). "Knockdown of lncRNA CCAT2 inhibited cell viability and cell cycle, and promoted the apoptosis and autophagy of gastric cancer cells may though blocking mTOR signaling." (PMID 34234860, 2021). "A series of preliminary experiments have suggested that ISL may inhibit the proliferation, migration, and invasion of MKN28 gastric cancer cells with PI3K/AKT/mTOR signaling pathway-mediated apoptosis and autophagy." (PMID 33494431, 2021). "Previous studies have shown that Akt/mTOR signaling pathway is closely related to autophagy, so we investigated whether narciclasine affected Akt/mTOR signaling pathway in gastric cancer cells." (PMID 34753517, 2021). "Taken together, these results suggest that LIT3527 is essential for gastric cancer cell survival through maintaining mTOR activity, suggesting that it may be clinically valuable as a therapeutic target for gastric cancer." (PMID 34234860, 2021). "In addition, TAMs-derived exosomes enriched apolipoprotein E (ApoE) promote the migration of gastric cancer cells by activation of PI3K/Akt/mTOR signaling pathway." (PMID 35250965, 2021). "Our findings illustrate for the first time that SS simultaneously induces apoptosis and protective autophagy by inhibiting Akt/mTOR pathway in gastric cancer cells, and SS may become a potential anticancer drug in treating gastric cancer in the future." (PMID 33708631, 2021). "Interestingly, gastric cancer mesenchymal stem cells (GCMSCs) impair NK cell function through mTOR signaling." (PMID 35250965, 2021). "In exploring the mechanism of narciclasine against gastric cancer, we found that narciclasine could inhibit the expression of p-Akt and p-mTOR." (PMID 34753517, 2021). "Contradictory to studies showing that AKT inhibitors can target multiple RTKs in various cancer cell types, the PI3K/mTOR inhibitor BEZ235 did not significantly alter the activity of different STAT3-regulating RTKs in PTEN-deficient gastric cancer cells." (PMID 33431808, 2021). "In addition, PB2 significantly decreased p-Akt and p-mTOR protein expression of gastric cancer cells." (PMID 33627124, 2021). "While, a recent study revealed that lncRNA FOXD1-AS1 could strengthen the interaction of eIF4E with eIF4G by activating the PI3K/AkT/mTOR pathway to promote gastric cancer progression and cisplatin resistance." (PMID 34454479, 2021). "Cy can also block the activation of the MET/AKT/mTOR axis, so it may be a potential therapeutic agent in the clinical treatment of gastric cancer." (PMID 34830011, 2021).